HMGB1 (high mobility group box 1)
Diseases named in the same sentence as HMGB1 in open-access papers (continued):
Sharing a sentence is not in itself a finding about the gene and the disease.
cancer (continued). "After reduction, HMGB1 is released by cancer cells into the extracellular space, where it interacts with RAGE, inducing Beclin-dependent autophagy." (PMID 38529373, 2024). "The translocation of HMGB1 to the cytoplasm has been proven to be an inducement of autophagy in many cancers." (PMID 37897664, 2024). "Studies have shown that HMGB1 plays a dual role in cancer by acting as an oncogene and tumor suppressor." (PMID 38725632, 2024). "Immunogenic death of cancer cells occurs with the release of risk associated molecular pattern (DAMP) molecules, including high mobility group box 1 (HMGB1), calreticulin (CRT), heat shock protein 70 (HSP70), and adenosine triphosphate (ATP)." (PMID 39231199, 2024). "While CALR exposure on cancer cells positively correlates with overall and progression-free survival (PFS), elevated HMGB1 levels has been associated with poor outcomes in some trials." (PMID 39572927, 2024). "Regarding area under the curve (AUC), HSP90 was the best at distinguishing the metastasis status of cancer patients, followed by HMGB1 and S100A9." (PMID 39768997, 2024). "All these cancer cells release HMGB1 in the extracellular microenvironment together with varying concentrations of thioredoxin and thioredoxin reductase." (PMID 38803493, 2024). "The findings provide additional mechanistic clues to HMGB1 functions in cancers, osteoclastogenesis, and likely in neuronal functions as well." (PMID 38580917, 2024). "It is demonstrated that molecules associated with NETs, such as high mobility group protein B1 (HMGB1), NE, and MMP9, can induce the proliferation and invasion of cancer cells, promote extracellular matrix remodeling, and modulate other inflammatory cells." (PMID 38167409, 2024). "The identification of HMGB1 as a promoter of angiogenesis in cancerous tissues provides a promising therapeutic target for cancer treatment." (PMID 38725632, 2024). "The combination of network pharmacology and natural active components will aid in exploring the mechanism and the detailed function of HMGB1 in cancer treatment." (PMID 37897664, 2024). "To gain insights into the relevance of the CXCL12/HMGB1 heterocomplex in cancer cell activities, we evaluated their capability to promote wound healing, migrate and invade the extracellular matrix." (PMID 38803493, 2024). "Bioengineered exosomes, painted with HMGB1, stimulate dendritic cells, enhance immunogenicity, and induce long-term immunity against cancer." (PMID 38566199, 2024). "To investigate the capability of the cancer cells to release HMGB1 in the microenvironment, and maintain it in the reduced form, we measured HMGB1, Trx and TrxR1 concentration in cell supernatants after overnight culture." (PMID 38803493, 2024). "Targeting HMGB1 from the early stages of carcinogenesis is useful for suppressing carcinogenesis and malignant phenotypes of cancer." (PMID 38999957, 2024). "Previous studies have shown that CIRT-damaged cancer cells participate in anti-cancer immunity by activating HMGB1/Toll-like receptor 4-mediated inflammatory responses." (PMID 38474078, 2024). "ATO inducing autophagy,apoptosis, iron death, and necrotic apoptosis pathways in cancer contributed to ATP release, HMGB1 version, CALR exposure of cancer cells, and IFNβ1 secretion of T cells." (PMID 39445013, 2024). "The mean concentration of HMGB1 among M0 and M1 cancer patients was 3.16 ± 0.29 and 3.44 ± 0.28 ng/mL; for HSP90, it was 16.83 ± 10.48 and 28.46 ± 7.36 ng/mL; and for S100A9, it was 5.04 ± 1.26 and 6.49 ± 2.24 ng/m, respectively." (PMID 39768997, 2024). "In the process of ferroptotic cell death, cancer cells release DAMPs such as high-mobility group box 1 (HMGB1), calreticulin (CRT), and adenosine triphosphate (ATP) into the TME." (PMID 39335181, 2024). "Human epithelial cells derived from breast (MCF-7 and MDA-MB-231) and prostate (PC-3) cancer express red-HMGB1 that is released in the extracellular microenvironment." (PMID 38803493, 2024).
cancer (continued). "HMGB1 is a highly conserved nuclear protein, which can participate in the development of cancer cells by regulating chromatin remodeling, gene transcription, and DNA replication." (PMID 38577597, 2024). "Despite the well-established roles of CXCL12 and HMGB1 in cancer metastasis, the role of the CXCL12/HMGB1 heterocomplex has never been investigated." (PMID 38803493, 2024). "Ferroptotic cancer cells release various immunostimulatory signals like high mobility group box 1 (HMGB1), calreticulin, ATP, and phosphatidylethanolamine." (PMID 38322268, 2024). "Studies have indicated that silencing S100B and HMGB1 delays diabetic complications and cancer progression." (PMID 39335163, 2024). "Measurement of the levels of inflammatory cytokines (HMGB1, tumor necrosis factor-alpha [TNFα]) and lipid peroxides (4HNE) in the cancer ascites showed increased levels for all cytokines compared with the control mouse peritoneal lavage." (PMID 39000167, 2024). "For instance, B2M, SLPI, BST2, GAPDH, S100A8, S100A9, and HMGB1, despite their beneficial roles in various infections, they contribute to cancer cell proliferation, invasiveness, reduced survival, and increased disease severity across different cancers." (PMID 38589404, 2024). "HMGB1 enhances autophagy and protects cancer cells from adriamycin-induced apoptosis by activating the AMPK/mTOR signaling pathway, which further contributes to chemoresistance in HCC cells." (PMID 38725632, 2024). "It has the capacity to enhance the proliferation and metastasis of OSCC by activating the HMGB1-mediated NF-κB signaling pathway, ultimately accelerating the malignant progression of cancer." (PMID 37897664, 2024). "Upon CIRT, cancer cells are damaged and release HMGB1, which is classified as an alarmin that is a cytosolic molecule in intact cells that is released upon cellular damage." (PMID 38474078, 2024). "One of the notable examples is the discovery of JG-98, a compound introduced by Jason Gestwicki, which dissociates the interaction between HSP70 and HMGB1, thereby effectively inhibiting relapse in pseudodormant cancer cell populations." (PMID 39682216, 2024). "GL suppressed STAT3-FoxP3 in Tregs and cancer cells, in addition to directly binding to HMGB1, leading to an anticancer effect." (PMID 39150932, 2024). "Interestingly, the temporal release of HMGB1 in the serum during cancer progression is associated with increased muscle autophagy with a consequent alteration in plasma-free amino acids and increased circulating glutamine availability to be used by cancer cells as an energy source." (PMID 39706853, 2024). "We found that HMGB1 is actively released by cancer cells together with the components of the thioredoxin system." (PMID 38803493, 2024). "A comprehensive analysis of serum cytokines and immune mediators in HNSCC patients revealed a spike in HMGB1 levels during cancer recurrence, which was accompanied by high levels of IL-4 and IL-10." (PMID 37897664, 2024). "Mechanistically, IGF2BP3 enhanced mRNA stability and promoted the expression of HMGB1 by binding to its mRNA, which is a factor that promotes inflammation and orchestrates tumorigenesis in many cancers." (PMID 38504159, 2024). "This review also highlights the current state of knowledge and gaps in our understanding of the role of HMGB1 in cancer, providing a foundation for future research and the development of novel therapeutic strategies." (PMID 38725632, 2024). "Our investigation further demonstrated that BBR effectively mitigated cancer-related myocardial damage by promoting the expression of miRNAs targeting HMGB1." (PMID 38731953, 2024). "To examine the effect of inflammatory cytokines, we treated the cells with HMGB1 and TNFα for 48 h at concentrations equivalent to those in the cancer ascites (50 μg/mL and 35 pg/mL, respectively) and examined the changes in 4HNE, PINK1, and Parkin." (PMID 39000167, 2024).
cancer (continued). "High-mobility group box-1 (HMGB1) is secreted by cancer cells and plays a pivotal role in promoting their proliferation, invasion, and metastasis by interacting with the receptor for advanced glycation end products (RAGE) expressed in cancer cells." (PMID 38731953, 2024). "As a multifunctional, cytokine-like alarmin, HMGB1 has contextual effects in cancer, favoring tumorigenesis via sustained inflammation, or, as proposed here, contributing to anticancer responses through immunogenic cell death and heightened IFN signaling." (PMID 39213189, 2024). "In pan-cancer, HMGB1 had the highest positive correlation with NUDT21, followed by TLR4, CD276, and TNFRSF4." (PMID 38349866, 2024). "In recent years, numerous reports have confirmed the importance of HMGB1 as a target for chemotherapy or as a resistance to radiation therapy in various types of cancer." (PMID 38725632, 2024). "In response to HMGB1 released by dying cancer cells, macrophages produce proinflammatory cytokines, such as IL-6 and TNF, via the Toll-like receptor 4-mediated pathway." (PMID 38474078, 2024). "Several studies suggested the potential for therapeutic intervention in targeting RAGE and HMGB1-mediated signaling pathways as a way of overcoming resistance to cancer therapy, primarily chemotherapy." (PMID 39830522, 2024). "Intracellular HMGB1 isolated from selected cancer cell lines is present as red-HMGB1, while both isoforms are present in primary CD3+ T cells purified from the blood of healthy donors." (PMID 38803493, 2024). "CGs have been shown to induce ICD biomarkers, such as CRT, HMGB1, and ATP, in several human cancer cell lines." (PMID 37705051, 2023). "Abscopal CD8+ T cell infiltration and cancer cell HMGB1 release and 4-HNE accumulation were significantly greater after histotripsy than checkpoint inhibition." (PMID 36756111, 2023). "Cisplatin treatment causes increased HMGB1 concentration in the nucleus, and cancer cells seem to partially survive treatment with cisplatin by transporting HMGB1 from the nucleus into the cytosol where it is then secreted into the extracellular milieu." (PMID 37759736, 2023). "The lactate metabolized by cancer cells stimulated M2 polarization and HMGB1 secretion by macrophages, aggravating the carcinogenic behaviors of cancer cells." (PMID 36709284, 2023). "To explore the biological function of circHERC1 in vivo, we subcutaneously inoculated NCI-H3255 cancer cells with altered expression of circHERC1, HMGB1 or FOXO1, into the flanks of nude mice." (PMID 37932766, 2023). "Median sRAGE concentration in the malignancy group was the second lowest, while HMGB1 and the HMGB1/sRAGE ratio were the second highest of all groups." (PMID 37894448, 2023). "Yet, several investigations have indicated that IL‐1β, IL‐18, and HMGB1 have a suppressive impact on cancer." (PMID 37752941, 2023). "The level of HMGB1 in cancer cells was increased by lactate-treated macrophages, while the increase was inhibited by glycyrrhizin." (PMID 36709284, 2023). "Meanwhile, HMGB1 neutralizing antibody efficiently attenuated the proliferation of pre-osteoclastic cells RAW.264.7, suggesting the dual role of HMGB1 in the invasion of cancer cells into the bone." (PMID 37511951, 2023). "Our previous study demonstrated that HMGB1 has a crucial role in the replication of KSHV in KSHV-producing cancer cell line." (PMID 37520371, 2023). "activited HMGB1 participates in the RNA metabolic process and thus promotes cancer cell proliferation and differentiation." (PMID 38028543, 2023). "High mobility group box 1 (HMGB1) has been demonstrated to induce the Toll-like receptor 4-mediated pathway to promote galectin-9 expression in cancer cells." (PMID 37371482, 2023).
cancer (continued). "HMGB1-overexpressing cancer cells concomitantly express the pro-metastatic Melanoma Inhibitory Activity (MIA) protein." (PMID 37511951, 2023). "With progression to CRC, there is an emergence of strong cytoplasmic HMGB1 (p < 0.001), pronounced at the leading cancer edge within CaP (p < 0.001), and reduction in nuclear HMGB1 (p < 0.001)." (PMID 36980751, 2023). "When cancer cells die from chemotherapy or radiotherapy, they release the high‐mobility group box 1 (HMGB1) protein." (PMID 36632988, 2023). "The addition of an HMGB1-neutralizing monoclonal antibody to a hypoxic cancer medium significantly inhibited the formation of NETs." (PMID 36942262, 2023). "Some studies have shown that HMGB1 can increase the infiltration of immune suppressive cells to weaken the anti-cancer effects of CD8+ T cells." (PMID 38288118, 2023). "In an attempt to revive their tumorigenic potential, the dying cancer cells release HMGB1, which binds to the cancer stem cells via the TLR2 receptor." (PMID 36635659, 2023). "Ferroptotic cancer cells can release several immunostimulatory signals, such as high mobility group box 1 (HMGB1), calreticulin, ATP, and phosphatidylethanolamine." (PMID 38125948, 2023). "HMGB1 (high mobility group box 1) is an abundant protein that regulates inflammation, proliferation, and metastasis in different cancer models." (PMID 37108476, 2023). "Nuclear HMGB1 in radiated cells promoted DNA damage repair, thereby protecting cancer cells against some radiation-induced damage." (PMID 36831371, 2023). "The upregulated HMGB1 was secreted into the extracellular environment, further increasing the level of HMGB1 in the cancer cells." (PMID 36709284, 2023). "Aberrant HMGB1 expression has been reported in different types of cancers, and many studies also verified the promoting role of HMGB1 in the genesis of some cancers including GBM." (PMID 36762036, 2023). "We compared the model’s simulation results under the HMGB1/cancer environment with published experimental data." (PMID 36993954, 2023). "The highly expressed genes in HMGB1+ Granulosa are mainly involved in cell division, Cell cycle (Mitotic), Retinoblastoma gene in cancer and other signaling pathways." (PMID 37564980, 2023). "As expected, FKPN plus laser irradiation treatment induced obviously enhanced high-mobility group box 1 (HMGB1) release in cancer cells." (PMID 37031242, 2023). "In this case study, we examined the impact of cancer-derived HMGB1 on the DC-T cell synapse interaction." (PMID 36993954, 2023). "We continued to investigate the biological significance of HMGB1 expression profile on the microenvironment at the invasive cancer margin within CaP lesions, by defining the inflammatory cell phenotype in this area." (PMID 36980751, 2023). "HMGB1 was secreted into the extracellular space of lactate-induced macrophages, further enhancing the malignant behaviors of cancer cells." (PMID 36709284, 2023). "The extracellular release of HMGB1 and ATP in the supernatant of 4T1 cancer cells was also evaluated through ELISA analysis." (PMID 37221237, 2023). "The pro-inflammatory molecules S100A8/A9 and high mobility group box protein 1 (HMGB1) and their receptor RAGE are strongly associated with the initiation and progression of most cancers." (PMID 36831371, 2023). "Analogous findings were obtained by the examination of the invasion potential of the cancer cells after HMGB1 silencing." (PMID 37511951, 2023). "Overexpression of HMGB1 in cancer tissue and increased HMGB1 serum levels have been documented for almost all solid tumors: colon, gastric, lung, breast, ovarian, pancreatic, and prostate." (PMID 36982351, 2023). "Human HMGB1 has been investigated in many chronic disorders and the number of publications about their role in cancer has reached higher than 1000 in the last years." (PMID 37110415, 2023).
cancer (continued). "For example, HMGB1 can be released by cancer cells in response to chemotherapy or radiotherapy to activate surrounding antigen-presenting cells to achieve antitumor immunity." (PMID 36707625, 2023). "It is evident that HMGB1 is ultimately involved in the development and progression of cancer as well as in angiogenesis and metastasis, pointing towards HMGB1 targeting as a potential therapeutic approach." (PMID 37511951, 2023). "HMGB1 influences multiple aspects of cancer progression, including DNA repair, transcription, angiogenesis, and metastasis." (PMID 37520371, 2023). "HMGB1 is a pro-inflammatory cytokine that has been extensively studied for the past years as a biomarker and a novel target for cancer therapies." (PMID 38003396, 2023). "In our next step, the induction of ICD by miR-CVB3 + CpGMel and single treatment was investigated by measuring DAMP release (i.e., CRT translocation to the surface of the cells, extracellular release of HMGB1 and ATP in treated cancer cells)." (PMID 37226233, 2023). "Apart from the three patients with inflammatory disease, women with malignant tumors had the highest concentration of HMGB1 and also the highest HMGB1/sRAGE ratios." (PMID 37894448, 2023). "HMGB1 overexpression is correlated to poor prognosis of many cancer, and HMGB1 is highly expressed in NSCLC cells and tissues." (PMID 37009887, 2023). "This study is likely relevant to some pathological contexts, where both HMGB1 and complement play a role, such as autoimmune, cancer, or neurodegenerative diseases, although this will need further confirmation." (PMID 37180096, 2023). "HSPs and HMGB1 can induce a Th1 type of immune response against cancer cells through binding to TLR4 receptors on DCs." (PMID 37705051, 2023). "When pyroptosis is activated, inflammatory mediators, such as IL‐1β, IL‐18, and HMGB1, are produced, all of which can have a positive impact on the progression of the cancer." (PMID 37752941, 2023). "ICD is a phenomenon that can change the composition of the cell surface and release cell soluble mediators such as ATP and high mobility group Box 1 (HMGB1), which are passively released by cancer cells undergoing ICD, triggering immune cell maturation." (PMID 37781042, 2023). "C‐ion irradiation releases high mobility group box 1 (HMGB1) from several cell lines of cancer, with the effect increasing with an increase in linear energy transfer." (PMID 37115713, 2023). "The HMGB1 expression is closely correlated with cancer-invasive and metastatic activity in HCC, prostate cancer, glioma, and nonsmall-cell lung cancer." (PMID 37945340, 2023). "Emerging research evidence indicates that HMGB1 can exhibit an extra- and intracellular role in cancer development, progression, and therapy." (PMID 37511951, 2023). "Extracellular HMGB1 can stimulate cancer invasion and metastasis via Toll-like receptor (TLR)-4 signaling and promotes the formation of NETs in vitro in a TLR-dependent manner." (PMID 36942262, 2023). "The presence and role of HMGB1(+) sEVs have been studied in various biological processes and diseases, including inflammation, cancer, and tissue repair." (PMID 37998605, 2023). "HMGB1 is considered a double-edged sword in cancer development since pro- and anti-oncogenic effects have been reported." (PMID 37110415, 2023). "The present study revealed that lactate produced by cancer cells enhanced the M2-type ratio of TAMs and elevated the level of HMGB1 in TAMs." (PMID 36709284, 2023). "HMGB1 was also reported to impair efferocytosis and to be involved in mediating immune tolerance of apoptotic cells or cancer cells through RAGE receptor." (PMID 37180096, 2023). "The role of HMGB1 in the etiology of cancer is complex because of its involvement in both DNA repair and extracellular signaling." (PMID 37759736, 2023). "In TNBC, the downregulation of miR-205 contributes to epithelial–mesenchymal transition and invasion of cancer cells by targeting the HMGB1-RAGE signaling pathway." (PMID 37681908, 2023).